SYP (synaptophysin)
Diseases named in the same sentence as SYP in open-access papers (continued):
Sharing a sentence is not in itself a finding about the gene and the disease.
neuroendocrine tumors (continued). "Besides, SP70 could also be helpful in identifying neuroendocrine neoplasm and fundic gland neoplasms, in combination with the neuroendocrine markers (ChromograninA and Synaptophysin)." (PMID 35468832, 2022). "Absence of synaptophysin-positive organoids could indicate selective outgrowth of non-neuroendocrine tumor cells or loss of synaptophysin expression during organoid culture." (PMID 33776923, 2021). "However, the updated WHO classification discourages the use of CD56 due to its non-specificity for neuroendocrine neoplasms (NENs) and instead advocates for CgA, SYP, and insulinoma-associated protein 1 (INSM1) as novel markers of neuroendocrine differentiation in the head and neck region." (PMID 39937015, 2025). "CgA, SYP, and CD56 expressions are routinely checked in surgical diagnostics, and positive immunoreactivity for these markers is commonly observed in neuroendocrine neoplasms." (PMID 39937015, 2025). "The morphology and immunohistochemistry type corresponded to a neuroendocrine tumor with higher malignancy, G2/G3 (CK19 (+), PanCK (+), synaptophysin (+), Ki67 up to 20%)." (PMID 40565772, 2025). "Synaptophysin and CD56 are generally more sensitive but lack specificity, often staining a broad range of non-neuroendocrine tumors." (PMID 40805240, 2025). "Neuroendocrine tumors expressing markers like SOX2, Synaptophysin, and Chromogranin A generally exhibit high aggressiveness and poor prognosis." (PMID 40735045, 2025). "Histopathologically, all tumors in our series were well-differentiated neuroendocrine tumors (WHO grade I), with synaptophysin positivity in all cases but variable chromogranin staining." (PMID 40271189, 2025). "Synaptophysin (SYN) marks neuroendocrine differentiation and aids in classifying neuroendocrine tumors." (PMID 41010919, 2025). "SCC usually exhibits pronounced keratinization and intercellular bridges and is diffusely positive for P63 and P40; adenocarcinoma is positive for TTF-1, napsin-A and neuroendocrine tumors are positive for CD56, synaptophysin, and chromogranin." (PMID 40746613, 2025). "Instead, the guidelines recommend CgA, SYP, and INSM1 expressions as immunohistochemical markers for neuroendocrine neoplasms of the head and neck region." (PMID 39937015, 2025). "Tumor cells in SCCOPT are generally positive for immunohistochemical neuroendocrine markers such as chromogranin A, synaptophysin, and CD56, demonstrating that SCCOPT represents a true neuroendocrine tumor." (PMID 40091949, 2025). "Pathological examinations showed that the bilateral breast masses were also positive for immunohistochemical staining of chromogranin A, synaptophysin, and CD56, leading to a diagnosis of bilateral breast metastasis of neuroendocrine tumor." (PMID 39292386, 2024). "Immunohistochemical markers such as chromogranin A, synaptophysin, and CD56 are neuroendocrine tumors’ most common positive markers." (PMID 39292386, 2024). "The chief tumor cells were positive for chromogranin A, synaptophysin, and CD56 antibodies, indicating a neuroendocrine tumor." (PMID 38721148, 2024). "In our cases, cytokeratin 7, TTF-1, p63, and p40 for lung tumors; CK7, GATA3, and GCDFP-15 for breast tumors; and cytokeratins, synaptophysin, chromogranin, and CD56 for neuroendocrine tumors were the most used markers." (PMID 35308701, 2022). "CgA and synaptophysin (SPY) are the two most widely used and reliable immunohistochemical markers for neuroendocrine tumors, including MTCs." (PMID 33485291, 2021). "Histopathological examination revealed the presence of a neuroendocrine tumor (CD56-, Ki67 1%, synaptophysin+, chromogranin+)." (PMID 33807230, 2021). "In contrast, UWG01CTC, isolated from a patient with neuroendocrine tumour, showed variable and weak cytokeratin (Cam5.2) immunostaining, with strong expression of neuroendocrine markers (CD56+, synaptophysin+, chromogranin A+)." (PMID 31953491, 2020).
neuroendocrine tumors (continued). "Immunohistochemically, grade 2 NETs are diffuse and positive for synaptophysin (Syn), chromogranin A (Cg A) and CD56, and the Ki-67 proliferation index indicates the malignant characteristics of neuroendocrine tumors." (PMID 31228945, 2019). "Other neuroendocrine markers such as synaptophysin and neural cell adhesion molecule (CD56) are general markers for neuroendocrine tumors besides PPGLs, as well as some adrenocortical tumors." (PMID 30150569, 2018). "Neuroendocrine tumors of the esophagus more frequently present in the middle of the esophagus and stain positive for CD56, synaptophysin, and chromogranin A." (PMID 30139375, 2018). "Immunohistochemically, NETs are positively stained by one or more neuroendocrine markers, and chromogranin A, synaptophysin, CD57, CD56, neuron specific enolase, and neurofilaments are important for evaluating neuroendocrine neoplasms." (PMID 27840746, 2016). "In contrast, SYP and CHGA respectively exhibited a 21- and 854-fold enrichment in neuroendocrine tumor lines compared to PCa models (P < 0.0001, Mann-Whitney U test)." (PMID 25859291, 2015). "Vesicle membrane proteins, such as synaptophysin and SV2, are used as general markers since they are present in virtually all neuroendocrine tumours." (PMID 12771991, 2003). "We incorporated immunostaining for thyroid transcription factor-1, chromogranin A, and synaptophysin, which yielded negative results, consequently excluding the possibility of high-grade neuroendocrine tumors." (PMID 40851880, 2025). "Napsin is positive in lung adenocarcinoma 23, CD56 and Synaptophysin are positive in neuroendocrine tumors 24 and CK20 is negative in squamous cell lung cancer." (PMID 41210693, 2025). "These clustered solid glands and anastomotic cords for which immunohistochemistry showed weak to moderate synaptophysin and/or CD56 positivity may have been misidentified as neuroendocrine tumors." (PMID 40692725, 2025). "This case corroborates earlier findings that cytokeratin 7 and pancytokeratin are often positive, while markers such as CDX2 and synaptophysin are negative, helping exclude adenocarcinoma and neuroendocrine tumors, respectively." (PMID 39860304, 2025). "Neuroendocrine markers like CD56, Chromogranin A (CgA), and Synaptophysin (Syn) are usually negative in PH, aiding in its distinction from neuroendocrine tumors despite potential histological similarities." (PMID 39228982, 2024). "IHC predominantly showed weak or negative staining for markers such as TTF‐1, CK5/6, p40, synaptophysin, chromogranin A, and CD56, which are often associated with adenocarcinoma, squamous cell carcinoma, and neuroendocrine tumors." (PMID 38124509, 2023). "Percutaneous biopsy of the liver mass demonstrated a well-differentiated neuroendocrine tumor (low grade) confirmed by immunohistochemistry (IHC) with strongly positive chromogranin and synaptophysin stain, negative CK20, CK7, LCA, and Ki-67 index of < 3%." (PMID 37670372, 2023). "Aberrant synaptophysin expression has been reported in non-neuroendocrine tumors but not in lymphoma or leukemia." (PMID 36401284, 2022). "The patient received left-sided pancreatic resection with the histological diagnosis of a well-differentiated neuroendocrine tumor (NET) of 0.6 cm that was immunohistochemically positive for chromogranin, synaptophysin, and insulin (NET G1, Ki-67 index 1%, pT1, pN0, L0, V0, Pn0, R0, G1)." (PMID 35406570, 2022). "Since SCLC is classified with neuroendocrine tumors, immunohistochemistry is very important in the diagnosis of SCLC, especially some neuroendocrine markers, such as Synaptophysin (Syn), Chromogranin A (CgA) and CD56 (an alias for neural cell adhesion molecule 1)." (PMID 34168983, 2021). "In one BBD, expanding the hepatic parenchyma, there was a poorly differentiated primary hepatic neuroendocrine neoplasm with rare lymphovascular invasion and negative immunolabeling for chromogranin, synaptophysin, AE1/AE3, CD3 and CD20." (PMID 29879222, 2018).
neuroendocrine tumors (continued). "Pathological analysis of the resected submucosal 1.8 cm tumour of the Meckel diverticulum and a metastatic local lymph node confirmed a well differentiated neuroendocrine tumour (grade I), whereas immunohistochemistry was positive for ACTH, chromogranin A and synaptophysin." (PMID 26610855, 2015). "The negative staining of synaptophysin and chromogranin A ruled out neuroendocrine tumors." (PMID 41515615, 2026). "While synaptophysin may be positive, especially in differentiating neuroendocrine tumors, chromogranin A (n = 2) is usually negative in SPN." (PMID 37733117, 2023). "Finally, SCLCs and large cell neuroendocrine carcinoma (LCNEC) are neuroendocrine tumors (NETs) that usually have neuroendocrine differentiation properties and are defined by the specific expression of chromogranin A (CHGA), synaptophysin (SYP), and neural cell adhesion molecule 1 (NCAM1)." (PMID 35962452, 2022). "Insulinoma-associated protein 1 (INSM1) has been considered as a novel immunostaining marker for neuroendocrine tumors (NETs) and is hypothesized to be more reliable than first-generation NET biomarkers, such as CGA (chromogranin A), SYP (synaptophysin), and CD56 (neural cell adhesion molecule)." (PMID 36531655, 2022). "Unfortunately, these markers are not always present in neuroendocrine tumors, and non-neuroendocrine tumors may also occasionally express Chromogranin A or Synaptophysin—making the diagnosis difficult to make for certain cases." (PMID 34571751, 2021). "All patients in our study were positive for CD56 and synaptophysin and most were negative for chromogranin A. These findings could have resulted in an incorrect diagnosis of neuroendocrine tumors." (PMID 33097069, 2020). "Furthermore, immunohistochemical findings showed an overexpression of synaptophysin and chromogranin A, indicative of a neuroendocrine tumor such as NEN or NEC, and not an adenocarcinoma." (PMID 32592083, 2020). "Besides typical morphology, well-known biomarkers for PCC/PGLs are positive immunohistochemistry for chromogranin A, synaptophysin, and S100; however, this does not allow differentiation from any other neuroendocrine tumors." (PMID 31597347, 2019). "Hence, the tumour was malignant and of neuroendocrine origin (as synaptophysin positive round to oval cells) without any evidence of primary tumour in other body sites, so the diagnosis was primary malignant neuroendocrine tumour of pleura." (PMID 27034865, 2016). "The absence of chromogranin and synaptophysin staining argues against a neuroendocrine tumor." (PMID 17338818, 2007). "However, the expression of synaptophysin and, to a lesser extent, also chromogranin A is not restricted to the neuroendocrine neoplasms, but may also be in a subset of non-neuroendocrine epithelial and non-epithelial neoplasms." (PMID 34647171, 2022). "The option of a neuroendocrine tumor was also ruled out given the negativity of CD56, synaptophysin, and progesterone." (PMID 39594178, 2024). "The liver lesions are metastases of a neuroendocrine tumor, positive for VIP and synaptophysin, but negative for NKX3.1." (PMID 33398457, 2021). "Immunohistochemistry revealed that this lesion was positive for synaptophysin and CD56, but negative for chromogranin as well as CD10, CD7, and CD20, consistent with a well-differentiated neuroendocrine tumor." (PMID 18430248, 2008).
Cognitive impairment (81 papers, 2012 to 2026). Abnormal cognition is characterized by deficits in thinking, reasoning, or remembering. "In the present study, the reduced presence of synaptophysin, a synaptic protein, in aged mice suggests that neuron dysfunction and synaptic loss occur in ageing-associated cognitive impairment." (PMID 39943805, 2025). "An acetate shortage in type 1 diabetes (T1D) mouse model was proven to enhance cognitive impairment and aggravate hippocampal synaptophysin (SYP) expression, associated with synaptic plasticity." (PMID 39092201, 2024). "Our results revealed that quercetagitrin significantly attenuated neuronal loss and cognitive deficits, with restored synaptophysin level in the brains of P301S-tau transgenic mice." (PMID 37175376, 2023). "In CLP-treated animals, reduced expression of SYP associated with synaptic plasticity and concomitant cognitive deficits can be observed in the hippocampus." (PMID 36530954, 2022). "Long-term acetate deficiency reduced hippocampal synaptophysin and facilitated cognitive impairments in mice." (PMID 34172092, 2021). "Infarct volume, cerebral edema, neurological deficits, cognitive impairment, and the level of Synaptophysin (SYP)、Growth associated protein-43 (GAP43) and neuronal nuclear antigen (NeuN) levels were measured to evaluate the effect of nicorandil." (PMID 33497397, 2021). "Significant loss of pre- and post-synaptic proteins, such as pre-synaptic density protein-95 and synaptophysin, respectively, has been linked to the cognitive impairments associated with AD." (PMID 33676561, 2021). "Moreover, synaptic loss was shown to be more related with AD-associated cognitive deficits, whereas synaptophysin increase was reported to correlate with cognitive recovery in model mice of AD." (PMID 27932977, 2016). "There were marked, age-related decreases in both PSD95 and synaptophysin beginning at 3 months, suggesting that hippocampal synaptic loss in these mice is an early event that occurs concomitant with the development of cognitive deficits." (PMID 25910195, 2015). "However, cognitive deficits emerged at the later time point and were associated with increased astrogliosis and reduction of synaptophysin staining in the hippocampi and cerebral cortices of exposed mice, 5 months post exposure." (PMID 25785457, 2015). "However, unknown processes underlie the changed expression of SYP protein in cognitive impairment associated with OSAS." (PMID 38858326, 2024). "Therefore, we determined whether genetic deletion of AQP4 in APP/PS1 mice advanced cognitive impairment was associated with more severe impairment of SYP and PSD-95." (PMID 26526066, 2015). "Research has shown that chronic acetate deficiency leads to reductions in hippocampal synaptophysin (SYP) levels and cognitive deficits, while exogenous acetate supplementation restores SYP levels and ameliorates cognitive deficits in type 1 diabetic mice." (PMID 40621927, 2025). "In a rat epilepsy model of cognitive impairment, pretreatment with AA increased levels of synaptophysin in the hippocampus and improved deficits in learning and memory." (PMID 40005058, 2025). "In this line, other authors have shown that chronic stress reduced synaptophysin expression in the hippocampus, correlating with depressive‐like behaviors and cognitive deficits." (PMID 41326981, 2025). "As previous studies reported, APP/PS1 mice exhibit cognitive deficits from 6 to 8 months of age and present decreased synaptophysin levels at 7–8 months." (PMID 39696695, 2024). "Hippocampal SYP expression is frequently observed to be diminished in animal models of cognitive deficits, whereas an increase in hippocampal SYP expression frequently accompanies cognitive recovery." (PMID 38858326, 2024).
Cognitive impairment (continued). "A marked loss of the presynaptic markers synapsin-1 and synaptophysin, as well as the postsynaptic marker PSD-95, is observed in individuals with mild cognitive impairment and is associated with both prodromal and advanced stages of AD." (PMID 39766244, 2024). "One of the specific presynaptic markers of neurons we studied was synaptophysin, which has been related to cognitive impairment in neurodegenerative diseases." (PMID 38472261, 2024). "The decreased synaptophysin expression in the CbCo, WB, and Hippo-CA1 regions suggested an overall reduction in synaptic density, a previously reported hallmark of cognitive impairment during the aging process." (PMID 38399364, 2024). "Neob pretreatment showed neuroprotective effects, as manifested in the attenuating ISO-induced expression of inflammatory-related proteins and synaptophysin in neonatal mice and attenuating changes in cognitive impairment in neonatal mice." (PMID 37120983, 2023). "CK improved cognitive impairment and increased postsynaptic density protein 95 and synaptophysin expression levels in mice with SCOP-induced cognitive dysfunction." (PMID 36873999, 2023). "In our previous study, using a mouse model of maternal sleep deprivation, we revealed that reduced levels of BDNF, PSD-95, and SYP in the hippocampus were strongly correlated with cognitive impairment." (PMID 38074521, 2023). "VX-765 treatment of aged J20 significantly reversed cognitive impairment, decreased synaptophysin immunoreactivity, and decreased dendritic spine density without increased altering pro-inflammatory cytokine levels, GFAP+-astrocytes and Iba1+-microglia numbers." (PMID 36220815, 2022). "Synaptic proteins including postsynaptic density protein (PSD)-95 and synaptophysin (SYN), with the reductions of these synaptic markers suggesting synaptic loss, potentially leading to cognitive impairment." (PMID 36337710, 2022). "Experiments with NMDA antagonists in mice treated with Aβ injection showed a decrease in synaptophysin immunostaining and cognitive impairments." (PMID 35783099, 2022). "Reduced SYP and cognitive deficits found in in sepsis-survivor animals can be prevented by treatments that reduce acute brain inflammation and oxidative stress." (PMID 36530954, 2022). "A decreased synaptophysin expression in the hippocampus of rodents with an obesity-induced cognitive deficit has already been reported." (PMID 36235574, 2022). "Sevoflurane induces increased methylation of the presynaptic marker synaptophysin at the mRNA level and enrichment by m6A, which decreases the expression of synaptophysin and leads to fine motor and cognitive impairment in young mice." (PMID 34766256, 2022). "BDNF increases synaptophysin and synaptobrevin levels which mediate neurotransmitter release; levels of synaptophysin and synaptobrevin are altered in cognitive disorders." (PMID 35492581, 2022). "Taken together, these results indicate that HupA attenuates TBI-induced cognitive deficits via up-regulation of SYP." (PMID 35096305, 2021). "In this study, we reveal that long-term acetate deficiency due to depletion of acetate-producing bacteria reduced hippocampal SYP level and accelerated cognitive impairment in T1D mice." (PMID 34172092, 2021). "Pre- or posttreatment with dexmedetomidine alleviated hypoxia-induced cognitive impairment, restored damaged synapses, and increased postsynaptic density-95 and synaptophysin protein expression following neonatal hypoxia." (PMID 33628369, 2021). "The study also found that a neuroprotective drug approved for type II diabetes (exendin‐4 polypeptide) prevented the induction of both synaptophysin reduction and cognitive impairment." (PMID 33629462, 2021). "Since 8 month old R26CT-CRE mice show cognitive impairments in spatial working memory as measured in the radial arm maze, levels of synaptophysin were measured as a qualitative indicator of synaptic density." (PMID 25178488, 2014).